CD4 (CD4 molecule)
Diseases named in the same sentence as CD4 in open-access papers (continued):
Sharing a sentence is not in itself a finding about the gene and the disease.
asthma (continued). "Independent of circulating immune memory cells, CD4+ TRMs are considered the primary reactive immune memory cells in the early stage, providing protection against RSV re-infection while contributing to asthma pathogenesis." (PMID 39632661, 2024). "Because CD4 T cells obtained from the lung in HDM-induced asthma models are not exclusively Th2 cells, the low activation of G3SE in lung CD4 T cells might result from the dilution of Th2 cells by other CD4 T cell subsets." (PMID 38969652, 2024). "Wisniewski and colleagues discovered that IFN-γ+CD4+ T cells were concentrated in the BALF of adult patients with severe asthma and that Th1 airway inflammation was evident in children with allergic and non-allergic severe asthma." (PMID 37377958, 2023). "Therefore, CD4– iNKT cells could serve as a potential target for immunotherapy, and strategies to exploit their function, such as the use of Tim-1–activating monoclonal Abs, should be explored as a possible therapeutic option for management of nonallergic asthma." (PMID 36477357, 2022). "Increases in CTLA-4 and TIM-3 expression in CD4+ T cells (not CD8+), as well as an increase in Th17 cells, may reflect asthma-related inflammation activity." (PMID 35029177, 2022). "To test whether the CD4+CD45RO+ circulating ILC3s are maintained after quitting smoking (i.e., whether they display a memory function), we divided the asthma patients according to their current smoking status (non-smokers, former smokers, and current smokers)." (PMID 35789151, 2022). "MSCs could suppress the proliferation of CD4+ T cells in PBMCs cultured in vitro after stimulation with antihuman CD3 and CD28 antibodies in both children with and without asthma." (PMID 31673233, 2019). "Surprisingly, asthma-induced resistance to S. pneumoniae is also observed in sensitized CD3−/− C57BL/6 mice and STAT-6−/− BALB/c mice, demonstrating that the protective effect of asthma is independent of Th2 CD4+ T cells." (PMID 30147700, 2018). "Additionally, we found that CD46 expression on CD4+ T cells was not dependent on serum 25-OH vitamin D levels in either HDs or AEA patients, even though AEA patients had decreased serum 25-OH vitamin D concentration, which was independent of asthma severity and division into CD46D/I groups." (PMID 39403120, 2024). "Thus, we sorted the iNKT, Treg, CD4 +T, and CD8+ T cells from the peripheral blood mononuclear cells (PBMCs)of 10 healthy volunteers, 10 patients with allergic asthma, and 10 patients with nonallergic asthma and examined their mRNA expression of ACC1 and PPARG." (PMID 37917548, 2023). "Since cigarette smoke appeared to augment sputum ILC3s and circulating CD4+CD45RO+ILC3s in patients with asthma (but not healthy individuals), we assessed whether the smoking amount, as expressed by Pack/Year (PY), correlated with the frequencies of these ILC3 populations in asthma patients." (PMID 35789151, 2022).
Sepsis (663 papers, 2006 to 2026). Sepsis is defined as life-threatening organ dysfunction caused by a dysregulated host response to infection. "In patients with HIV-associated sepsis, the CD4 T-cell count and TyG index not only effectively distinguish clinical phenotypes with distinct prognostic outcomes, but their combination also serves as a valuable prognostic tool in this population." (PMID 41601726, 2026). "ERS is a key regulator of T cell metabolism in sepsis and promotes sepsis-associated immunosuppression (SAI) by inducing CD4+ T cell apoptosis." (PMID 40933998, 2025). "Sepsis is associated with apoptosis and functional changes in immune cells, including CD4+ and CD8+ T cells, B cells, and dendritic cells." (PMID 40386708, 2025). "The effect of sepsis on the induction of T1D in our study is associated with the altered activation profile of T cells, CD4+ T cells in particular, in the pancreas-related lymphoid organs." (PMID 41142792, 2025). "Ulteriorly, depletion endogenous CD4+ T cells alleviated susceptibility of LPS-induced sepsis in Dock2−/− mice." (PMID 40510337, 2025). "This depletion leads to a transient decline in the number of pre-existing memory CD4+ T cells, along with sustained dysfunction, which increases susceptibility to secondary infections in sepsis survivors." (PMID 40124361, 2025). "These CD4+ T cell alterations in sepsis are accompanied by widespread loss of cytotoxic cells such as CD8+ cytotoxic cells, NK cells and γδ T cells." (PMID 41208955, 2025). "In sepsis, monocyte depletion is associated with ferroptosis, and ferroptosis in CD4 + T cells correlates with disease progression." (PMID 40832104, 2025). "Memory CD4+ T cells and regulatory CD4+ T cells were positively associated with age in sepsis alone." (PMID 39935482, 2025). "For instance, in murine models of sepsis, hyperactivation of the mTOR signaling pathway has been shown to induce pyroptosis in CD4+T cells, exacerbating immunosuppression associated with sepsis." (PMID 41041277, 2025). "The apoptosis of B and CD4+ T cells, as well as immunosuppression, have been previously associated with worst outcome in patients with sepsis." (PMID 40241761, 2025). "In adaptive immunity, sepsis-induced apoptosis in septic shock patients causes lymphopenia, affecting all T cell subsets (CD4+, CD8+, and natural killer cells) except T regulatory cells, which promotes immunosuppression." (PMID 40755920, 2025). "Our study reveals an elevation of NETs in a late-stage mouse model of sepsis, contributing to increased Treg differentiation, a process associated with altered cholesterol metabolism in naive CD4+ T cells mediated by NETs." (PMID 38888975, 2024). "Results showed the numbers of lymphocytes, CD3+ T cells, CD4+ T cells, and NK cells were significantly associated with the mortality of sepsis." (PMID 38669099, 2024). "Loss of TIGIT augments CD4+ T cell proliferative and effector competence in bacteria clearance and thus confers protection in sepsis." (PMID 38545097, 2024). "Third, while the study validated the association between CD4 cell count levels in the lymphocyte subgroups and the risk of sepsis from a genetic perspective, the specific mechanism underlying this is complex." (PMID 39465765, 2024). "In conclusion, our study strongly supports that CD4+ T lymphocyte counts are associated with mortality in sepsis patients." (PMID 39290582, 2024). "Neutrophil-derived NETs have been implicated in the progression of sepsis and are known to bridge innate and adaptive immune responses by regulating CD4+ T cell apoptosis." (PMID 38888975, 2024). "Apart from the capacity of NETs to influence the differentiation and function of Tregs in the late stage of sepsis, we also elucidated the specific mechanisms underlying the differentiation of naive CD4+ T cells into Tregs in the presence of NETs." (PMID 38888975, 2024).
Sepsis (continued). "We also found the levels of Hb (P = 0.022), Plt (P = 0.017), lymphocytes (P < 0.001), CD3+ T cells (P < 0.001), CD4+ T cells (P < 0.001), and NK cells (P < 0.001) were negatively associated with the 28-day mortality of sepsis." (PMID 38669099, 2024). "In conclusion, the study ascertains the causal correlation between CD4 cell count levels and sepsis risk from a genetic standpoint." (PMID 39465765, 2024). "Sepsis also causes global changes in expression of transcription factors that affect CD4+ T cell effector responses that we observed via pathway analysis." (PMID 39691721, 2024). "This study established a causal correlation between the absolute count of CD4 Treg within lymphocyte subgroups and sepsis risk, aligning with prior research findings." (PMID 39465765, 2024). "Although naïve cells are particularly susceptible to sepsis-induced apoptosis and phenotypic changes, a numerical loss of existing memory CD4+ and CD8+ T cells has also been demonstrated." (PMID 38197178, 2024). "The 2-sample Mendelian randomization study indicated a causal relationship between the level of CD4 Treg AC and the increased risk of sepsis." (PMID 39465765, 2024). "Sepsis is associated with a strong depletion of CD4+ and CD8+ T cells, B cells and dendritic cells (DCs) as a result of apoptosis." (PMID 39267971, 2024). "Among these, terminal differentiation (TD) CD4+ %T cells demonstrated bidirectional MR causal associations with sepsis." (PMID 38601150, 2024). "Much of our analysis of CD4+ T cells, whose loss and dysfunction after sepsis are well understood to be related to patient mortality, revealed results similar to the published literature." (PMID 39691721, 2024). "PGD2, an eicosanoid that exhibits some selectivity for sepsis due to COVID‐19, appears to exhibit a particular influence on non‐B non‐T cells and CD4+ T cells while the EC, AEA is linked to CD8 T cell activation." (PMID 37948331, 2023). "PD-1 expression increases in CD4+T cells in patients with sepsis and is associated with a poor prognosis." (PMID 37292207, 2023). "To test this, we used the cecal ligation and puncture model as a proxy for polymicrobial sepsis and assessed the phenotype of CD4+ Tregs in VISTA-gene deficient (VISTA-/-) and wild-type mice." (PMID 35401514, 2022). "Post-mortem analyses of spleen and lymph nodes taken from patients who died from sepsis showed a significant loss of CD4+ and CD8+ T cells." (PMID 36556399, 2022). "As we know, there is no study that has compared the efficacies between cholecalciferol and calcitriol in sepsis-induced CD4+ T cell changes and associated intestinal inflammation and damage." (PMID 36079813, 2022). "Multivariate regression analysis indicated that the increased level of mTOR and PD1, as well as reduced level of IFN-γ in CD4+ T cells were independent risk factors for 28-day mortality in patients with sepsis." (PMID 35898496, 2022). "Autophagy is regarded as a protective mechanism from apoptosis in CD4 + T cells during sepsis, and deficient autophagy accelerates apoptosis." (PMID 35435531, 2022). "Leukopenia is relatively frequent, with lymphocytopenia occurring in 90% of TEN cases, which can be explained by the depletion of CD4+ T cells; on the other hand, neutropenia is found in 30% of patients and is, generally, associated with sepsis." (PMID 39599955, 2022). "This is the first time that mTOR proved to be involved in the CD4+ T cell apoptosis caused by ROS-mediated ERS in sepsis." (PMID 35915740, 2022). "A previous study has found that lymphocytopenia and immunosuppression in patients with advanced sepsis were associated with CD4+ and CD8+ T cell apoptosis." (PMID 35178128, 2022). "Previous studies have implicated that the number of CD4+ T cells was one of the effective predictors of poor prognosis in sepsis." (PMID 35178128, 2022).
Sepsis (continued). "The present study, together with our previous research on the abnormal apoptosis mechanism in CD4+ T cells, revealed the complete process underlying sepsis-related CIRP–ROS-ERS–mTOR–CD4+ T cell apoptosis." (PMID 35915740, 2022). "A decrease in the CD4+/CD8+ T-cell ratio in trauma patients is directly related to the risk of sepsis and is correlated with the occurrence of MODS." (PMID 36209190, 2022). "Increased BTLA expression on circulating CD4+ T cells in sepsis patients was associated with nosocomial infection." (PMID 36518755, 2022). "Reduced CD4+ T cell absolute number is an independent risk factor that influences the outcome of sepsis patients." (PMID 35915740, 2022). "In murine sepsis models, there is a significant loss of CD4+ T cell frequency which impacts survival." (PMID 35401514, 2022). "In line with previous reports, the reduction in the total number of conventional DCs in the spleen was mainly based on a loss of the CD4+ DC2 subset that was evident 24 h after induction of sepsis and that was maintained at least 4 days after CLP." (PMID 36148245, 2022). "For instance, sepsis induced by Gram-positive bacteria Streptococcus pneumoniae and Staphylococcus aureus caused an extended reduction (≥14 days) for CD4+, CD8+, total T lymphocyte, and NK cellular populations." (PMID 36199798, 2022). "Previous studies have suggested that immune cell apoptosis including CD4 T cells, B cells and dendritic cells is a possible cause of progressive organ failure in sepsis." (PMID 35502484, 2022). "Sepsis caused prominent cell loss in the CD4+ and CD8+ T cell, NK cell, and B cell compartments in PH mice and CA septic mice." (PMID 34100383, 2021). "Sepsis increases apoptosis which can lead to deleterious defects in CD4+T cell number, with greater apoptosis associated with increased mortality." (PMID 33532141, 2021). "In our study, CLP-induced sepsis significantly decreased the ratio of CD4+ cells, increased the ratio of CD8+ cells, causing a significant decrease in the ratio of CD4+/CD8+ in rats." (PMID 34057015, 2021). "Treatment of CA septic animals but not PH septic animals with anti-TIGIT mAb significantly reversed sepsis-induced loss of CD4+ T cells, CD8+ T cells, Foxp3+ Treg, and CD19+ B cells in the spleen, which was the result of decreased caspase-3+ apoptotic cells." (PMID 34100383, 2021). "Triggering events and causative microbes for studies that suggested CD4 T cells from recovered sepsis patients exist in a state of global anergy varied among patients." (PMID 32733454, 2020). "CD4+ T cells seem to be the most susceptible to cell death during sepsis and have ensuing defective secretory profiles and functions." (PMID 33336293, 2020). "In human, depletion of both B cells and CD4+ T lymphocytes caused by sepsis-induced apoptosis were reported." (PMID 32983116, 2020). "Our data demonstrate sepsis leads to dramatic and transient decline in pre-existing memory CD4 T cell numbers, with sustained functional impairments, which contribute to the overall increased susceptibility to secondary infections in sepsis survivors." (PMID 32903436, 2020). "Studies demonstrate that sepsis causes significant depletion of CD4 and CD8 T cells, which is a major driver of impaired immune responses and reduced host antimicrobial capacity." (PMID 33613563, 2020). "Apoptosis of CD4+ T cells plays a central role in the progression of sepsis because it is associated with subsequent immunosuppression and the lack of specific treatment." (PMID 31263382, 2019). "The present study revealed the impact of Mdivi-1 on the apoptosis of CD4+ T cells in sepsis and the potential underlying mechanisms." (PMID 31263382, 2019). "Sepsis causes a significant reduction in the numbers of CD4 T cells, which affects host response to infection." (PMID 30052667, 2018).
Sepsis (continued). "There is extensive evidence that sepsis causes profound loss of CD4 and CD8 T cells; surviving T cells are poorly functional and exhibit an “exhausted” phenotype that mimics pathophysiological features seen in malignancy." (PMID 29944697, 2018). "Here we postulated that these differences in systemic immunity in cancer hosts are associated with the altered CD4+ T cell response during sepsis." (PMID 29338031, 2018). "When evaluating the CD4+ cells that survive, there is reduced Th1- and Th2-associated cytokine production both during and long after sepsis subsides." (PMID 29163354, 2017). "Taken together, these data indicate a critical role of Mfn2 in CD4+ T cell apoptosis in sepsis and the underlying mechanism of autophagy deficiency." (PMID 29358849, 2017). "Expression of the E3-Ubiquitin Ligase has been linked to CD4 T cell hyporesponsiveness during sepsis and chronic murine schistosomiasis." (PMID 28114324, 2017). "Oropharyngeal candidiasis (p˂0.001) and sepsis (p = 0.042) also remained significant risk factors of PrevTB after controlling for viral load and CD4 counts in the regression models." (PMID 27232185, 2016). "Sepsis induces a comprehensive loss of myeloid cells and lymphocytes including CD4+ and CD8+ T cells." (PMID 27056672, 2016). "It is also important to note that oropharyngeal candidiasis and sepsis also remained as independent risk factors, even after controlling for CD4 counts and viral load." (PMID 27232185, 2016). "HEU infants born to severely immunocompromised mothers (CD4 < 200 cells/mm3) in a South African cohort were found to be at higher risk of developing early- and late-onset sepsis than those born to mothers with CD4 > 350 cells/mm3." (PMID 24885498, 2014). "These mice showed earlier onset of mortality than wild type mice and had overall increased mortality after sepsis, accompanied by loss of CD4+ and CD8+ T cells, and increased cellular apoptosis." (PMID 25029098, 2014). "Among sepsis patients, the development of persistent or new nosocomial infection was associated with lower Day 1 to 2 CD4+ T-cell cytokine-production capacities." (PMID 25005517, 2014). "Secondly, elimination of the autophagy protein ATG7 with the use of T cell-specific Atg7-knockout mice resulted in an increase in sepsis-induced mortality and a loss of CD4+ and CD8+ T cells to apoptosis." (PMID 25029098, 2014). "• Among children with sepsis, suppressed CD4+ T-cell cytokine-production capacity is associated with the development of persistent or new nosocomial infection." (PMID 25005517, 2014). "At multivariate analysis, only preoperative WBC, hemoglobin and CD4 remained significantly (P<0.05) associated with sepsis." (PMID 23181440, 2012). "The hospital mortality of HIV-infected patients who were admitted to the ICU was associated with low CD4 lymphocyte count and the diagnosis of sepsis." (PMID 21871086, 2011). "Previously published reports indicate that CD4+ T cells exhibit numerous functional deficiencies in response to the intense physiological stresses associated with sepsis, burn injury and trauma." (PMID 21655295, 2011). "• The hospital mortality of HIV-infected patients who are admitted to the ICU is associated with low CD4 lymphocyte count and the diagnosis of sepsis." (PMID 21871086, 2011). "This study aimed to assess whether combining the TyG index, a surrogate for insulin resistance, with CD4+ T cell count enhanced early prediction of 28-day mortality risk in adults hospitalized with HIV-associated sepsis." (PMID 41601726, 2026). "Among 1,278 patients with HIV-associated sepsis, 847 had CD4 counts <50 cells/μL." (PMID 41601726, 2026). "Against this backdrop, the purpose of this study was to assess whether the TyG index and CD4+ T-cell count at the onset of sepsis independently predict 28-day all-cause mortality in people living with HIV." (PMID 41601726, 2026).